MTOR (mechanistic target of rapamycin kinase)
Diseases named in the same sentence as MTOR in open-access papers (continued):
Sharing a sentence is not in itself a finding about the gene and the disease.
melanoma (continued). "Recently, we observed instances of primary cross-resistance to a MEK1/2 (AZD6244) and to a dual PI3K/mTOR (BEZ235) inhibitor in some melanoma cell lines." (PMID 26678033, 2016). "AZD6244-BEZ235, but not PLX4720-BEZ235, downmodulated the anti-apoptotic gene Bcl-2 and the mTOR interactor 4EBP1, as well as β catenin, a gene that impairs T cell-mediated immune response in melanoma, and LEF-1 a β catenin interacting partner." (PMID 26678033, 2016). "The fact that A-SMase in melanomas affects mTOR-regulated autophagy and plays a central role in cisplatin efficacy encourages pre-clinical testing on the modulation of A-SMase levels/activity as possible novel anti-neoplastic strategy." (PMID 27107419, 2016). "Inhibitors of PI3K/mTOR in combination with BRAFi eradicate pS6high cell subpopulations and potentiate anti-cancer effects in melanoma protected by the fibroblasts." (PMID 26918352, 2016). "Upon treatment with BRAFi, such melanoma cells maintain high levels of phospho ribosomal protein S6 (pS6), i.e. active mTOR signaling, which is suppressed in the BRAFi sensitive cells without stromal contacts." (PMID 26918352, 2016). "In this context, ligation of PD-1 with PDL-1 in melanoma cells augments the mTOR-signaling pathway and promotes the expression of glycolytic enzymes, which correlate with tumor growth." (PMID 27510264, 2016). "The inhibition of the Akt/mTOR/P70S6K kinase-signaling pathway by curcumin was also reported in human melanoma cells." (PMID 27834913, 2016). "MCL-1 is cooperatively regulated by MEK and mTOR in the MEK driven OCM1A melanoma cell line, and mTOR is known to induce cell survival through upregulation of MCL-1 protein." (PMID 25955301, 2015). "Alterations in the PI3K/AKT/mTOR pathway have been shown to be operative in multiple tumors including melanoma." (PMID 25886620, 2015). "High PIP3 levels sequentially activate downstream AKT (mainly, AKT3 in melanoma) and its substrate mTOR, modulating the synthesis of proteins involved in cell growth and survival as well as in apoptosis." (PMID 26322273, 2015). "Combining vemurafenib with an mTOR or PI3K inhibitor improved cell killing in BRAF-mutant melanomas with ERK-independent resistance to MAPK inhibition." (PMID 26639561, 2015). "Using this approach, we have discovered that melanoma and angiosarcoma were insensitive to mTOR inhibition." (PMID 25955301, 2015). "Since we found that NexrutineR inhibits cell survival and growth, we focused on signaling through the PI3K/AKT/mTOR pathway, which is a major player in growth and survival of cancer cells including melanoma." (PMID 25749517, 2015). "In this regard, NexrutineR holds great promise for its ability to disrupt redox homeostasis and target the ROS/mTOR axis with particular implication for melanoma and other cancers." (PMID 25749517, 2015). "The effect of mTOR inhibitors was also minor compared to MEK inhibitors in NRAS mutant melanoma cells." (PMID 26544513, 2015). "Taken together, these data suggest that NexrutineR inhibits PI3K/AKT/mTOR signaling in a ROS-dependent manner in melanoma cells." (PMID 25749517, 2015). "In melanoma cells, metformin can inhibit mTOR independently of AMPK activation and induces cell-cycle arrest, autophagy, and cell death." (PMID 26322273, 2015). "Increased oxidative stress in melanoma cells inhibited PI3K/AKT/mTOR pathway through disruption of mTORC1 formation and phosphorylation of downstream targets p70S6K, 4EBP1 and rpS6." (PMID 25749517, 2015). "Our data show that a low dose of an mTOR inhibitor can dramatically enhance angiosarcoma and melanoma response to MEK inhibition, potentially widening the field of applications for MEK-targeted therapy." (PMID 25955301, 2015). "Phosphatidylinositol 3-kinase (PI3K)-AKT-mammalian target of rapamycin (mTOR) signaling pathway is important for melanoma initiation and progression." (PMID 26204252, 2015).
melanoma (continued). "In sum, we conclude that combining PI3K/Akt/mTOR inhibition with DC-melanoma fusion cell-based cancer vaccination appears to be a promising strategy and warrants further studies in vitro and in animal models." (PMID 26605345, 2015). "Overall, our results illustrate the importance of disruption of the intrinsically high oxidative stress in melanoma cells to selectively inhibit their survival mediated by PI3K/AKT/mTOR." (PMID 25749517, 2015). "One of the most promising approaches to sensitize melanoma cells to TRAIL-mediated cell death is the simultaneous targeting with inhibitors of either MEK/ERK or PI3K/mTOR pathways." (PMID 24920406, 2014). "This study investigated B16F10 melanoma cell death induced by melatonin combined with endoplasmic reticulum (ER) stress through the PI3K/Akt/mTOR pathway." (PMID 24647338, 2014). "Combined targeting of MEK and PI3K was superior to MEK and mTOR inhibition in NRAS-mutant melanoma cell lines and xenografts." (PMID 24743024, 2014). "In this study, the PI3K/Akt/mTOR pathway in melanoma cells was demonstrated to be a new therapeutic target for melanoma treatment." (PMID 24647338, 2014). "Taken together, these results indicated that co-targeting of MEK and PI3K/mTOR pathways and of the death receptor pathway has synergistic anti-melanoma activity likely mediated by enhanced induction of caspase-dependent apoptosis." (PMID 25275595, 2014). "In this study, we found that combined melatonin and ER stress treatment induced cell death in B16F10 melanoma cells through the PI3K/Akt/mTOR pathway." (PMID 24647338, 2014). "Specific clinical studies with regard to the mTOR inhibitor have been performed in malignant melanoma." (PMID 24348822, 2014). "It has been previously reported that the mTOR pathway is activated in malignant melanomas in contrast to benign melanocytic nevi." (PMID 24348822, 2014). "In this study, we demonstrated that a combination of melatonin and thapsigargin or tunicamycin induced cell death through the PI3K/Akt/mTOR pathway in B16F10 melanoma cells." (PMID 24647338, 2014). "The PI3K/Akt/mTOR pathway is frequently activated in human melanoma and is a possible therapeutic target for melanoma treatment." (PMID 24647338, 2014). "Taken together, these results indicated that association of MEK and PI3K/mTOR inhibitors with TRAIL, or MEK blockade with TRAIL, leads to synergistic anti-tumor effects on most melanoma cell lines, even on inhibitor- or TRAIL-resistant ones." (PMID 25275595, 2014). "Taken together, these results demonstrate the critical role of the PI3K/Akt/mTOR signaling cascade in melanoma progression, further supporting the development of a combinatorial strategy to target this pathway at multiple levels." (PMID 24920406, 2014). "In 49 melanoma cell lines, we found independent susceptibility profiles for response to the MEK1/2 inhibitor AZD6244, the PI3K/mTOR inhibitor BEZ235 and the death receptor ligand TRAIL, supporting the rationale for their association." (PMID 25275595, 2014). "This review pays attention on the clinical application of both Raf/MEK/ERK and PI3K/AKT/mTOR pathway inhibitors as novel treatment strategy for melanoma." (PMID 24899250, 2014). "The sensitivity profiles to the inhibitors of the two key NRAS downstream signaling cascades MAPK and PI3K/AKT/mTOR were similar to sensitivity profiles found in NRAS mutant melanoma." (PMID 25277205, 2014). "The RAS/RAF/MEK/ERK and PI3K/v-Akt murine thymoma viral oncogene (Akt)/mTOR pathways are the two major signal transduction cascades that are often hyper-activated in various human cancers, including melanoma." (PMID 24920406, 2014).
melanoma (continued). "In conclusion, further preclinical and clinical investigation of coordinate autophagy and PI3K/AKT/mTOR inhibition as a rational approach to improve therapeutic outcomes in advanced melanoma is warranted." (PMID 23383069, 2013). "The PI3K-AKT-mTOR pathway is constitutively activated in many melanomas, leading to increased cell growth, proliferation, and survival, and mTOR inhibition with Temsirolimus or sirolimus [rapamycin] has antitumor activity in preclinical models of melanoma." (PMID 24047116, 2013). "Due to the lack of PI3K and AKT inhibitors currently available for clinical trial evaluations in melanoma, attention has turned to mTOR for which several inhibitors are under development." (PMID 23515890, 2013). "We are unaware of prior reports of miRNA profiling of melanoma metastases after mTOR or VEGF inhibition." (PMID 24047116, 2013). "Pharmacologic inhibition of PI3K/AKT/mTOR pathway components thus becomes an attractive approach for melanoma treatment." (PMID 23383069, 2013). "We treated melanoma cell lines displaying different BRAF and GNAQ mutational status with the mTOR inhibitor RAD001 and with the MEK1/2 inhibitor U0126 and evaluated the effects in the growth of the cell lines and in mTOR and MAPK pathway effectors expression." (PMID 23904987, 2013). "Dysregulated, active PI3K/AKT/mTOR signaling promotes cell proliferation and survival, and is found in a wide range of tumor types, including melanoma." (PMID 23648148, 2013). "In a previous study we analyzed the interactions of PG and OBX with several kinases, demonstrating that the mammalian target of rapamycin (mTOR) is a molecular target of both PGs in melanoma." (PMID 23460874, 2013). "The effects of the mTOR pathway inhibitor RAD001 on melanoma cell growth in monolayer culture was determined by SRB assay." (PMID 23904987, 2013). "Recently, M. Espona-Fiedler identified the mammalian target of rapamycin (mTOR) as a candidate molecular target of PGs in melanoma cells." (PMID 23799011, 2013). "While this mTOR inhibitor study diminishes the therapeutic value of targeting the PI3K pathway in melanoma, preclinical evidence has shown, however, that co-targeting this pathway along with the MAPK pathway remains an important therapeutic option." (PMID 23515890, 2013). "Treatment of melanoma patients with the mTOR inhibitor sirolimus in combination with carboplatin and paclitaxel displayed significant tumor regression." (PMID 23372575, 2012). "In malignant melanoma, more than 50% of tumors carry BRAFV600E mutation and 70% have elevated AKT phosphorylation and/or activated mTOR activities." (PMID 22880048, 2012). "Although phase II clinical trials with mTOR inhibitors alone yield minor responses and/or high toxicity in melanoma patients, phase II clinical trials combining temsirolimus and sorafenib are ongoing (NCT00349206)." (PMID 22408430, 2012). "Subsequent studies have shown that inhibition of mTOR signaling with lonafarnib augments sorafenib-induced apoptosis in melanoma cell lines." (PMID 23228035, 2012). "Another possibility in targeting the AKT pathway in melanoma is through inhibition of mTOR signaling using rapamycin or rapamycin analogs." (PMID 23372575, 2012). "Recent studies in melanoma have indicated that some components of the PI3K pathway (PTEN, MTOR, IRS4, PIK3R1, PIK3R4, PIK3R5 and NFKB1) are co-mutated in 17% of BRAF V600E mutant and 9% of NRAS mutant melanomas." (PMID 23006971, 2012). "Phase 2 study for melanoma patients was tested by using the combination of bevacizumab, an inhibitor of angiogenesis, and everolimus, an inhibitor of mTOR which is a downstream target of PI3K/PTEN/AKT signaling." (PMID 22013435, 2012). "Our study adds an additional rationale to support combination therapies with RAF/MEK inhibitors and PI3K/AKT/mTOR inhibitors for the treatment of melanoma patients." (PMID 22880048, 2012).
melanoma (continued). "In this review, we aim to survey relevant research, the molecular mechanisms of signalling, including upstream activation and downstream effectors, and the role of mTOR in cancer, mainly in melanoma." (PMID 22408430, 2012). "The combination of trametinib and the PI3K/mTOR dual inhibitor GSK2126458 also enhanced cell growth inhibition in these B-Raf inhibitor-resistant BRAF mutant melanoma lines." (PMID 23085539, 2012). "Rapamycin enhanced the activity of the dual PI3K/mTOR inhibitor NVP-BEZ235 in inhibiting the growth of melanoma." (PMID 23455493, 2012). "Phosphatidylinositol 3 kinase (PI3K)/Akt/mammalian target of rapamycin (mTOR) is an important pathway inducing the transformation and growth of melanoma." (PMID 24281076, 2010). "Mechanistically, it seems that combined MEK/mTOR inhibition reduces the expressions of Mcl-1 and Bcl-2, two proteins that are known to suppress apoptosis induction in melanoma cells." (PMID 19156138, 2009). "Our interpretation of this result is that mTOR activity is required to maintain the phosphorylation of ERK in melanoma cells." (PMID 16255777, 2005). "Another molecular pathway commonly mutated (30–60%) in melanomas involves loss of the PTEN tumor suppressor gene, which can lead to constitutive activation of the mTOR kinase signaling pathway." (PMID 16255777, 2005). "Together, these findings argue against use of CCI-779 as a single agent, but support investigation of mTOR inhibitors as part of combination therapy for treatment of patients with malignant melanoma." (PMID 16255777, 2005). "What was unexpected was that each of the drugs inhibited phosphorylation in both the Raf and mTOR pathways, suggesting there was interdependence or cross-talk between these pathways in melanoma cells." (PMID 16255777, 2005). "In the future, targeting both the CAF/MEK/ERK and PI3K/AKT/mTOR might serve as a therapeutic option for the treatment of NRAS‐mutant melanoma." (PMID 41492362, 2026). "Heightened AKT/mTOR activity occurs in about 70% of metastatic melanoma and it is reported that AKT activation is associated with a change from the radial growth phase of melanoma to the vertical growth phase." (PMID 40710294, 2025). "Renin–angiotensin system inhibition may affect not only AT1R and AT2R signaling, but also its interactions with the overactive Ras/RAF/MAPK/ERK and PI3K/AKT/mTOR pathways in melanoma." (PMID 39941158, 2025). "Moreover, in the current study, melittin has been shown to act against melanoma A375 cells by downregulating PI3K/AKT/mTOR and MAPK signaling pathways." (PMID 40932870, 2025). "Other dysregulated pathways in melanoma include PI3K/AKT/mTOR and JAK/STAT." (PMID 40710294, 2025). "In addition, the α3β1/α11β1 integrins/Src/YAP pathway drove dual drug resistance to MAPK and PI3K/mTOR inhibitors in the melanoma cell lines SKMEL28 and WM2664." (PMID 40243917, 2025). "Rapamycin primarily inhibited melanoma by targeting the mTOR pathway." (PMID 40909968, 2025). "We found that both concentrations of salidroside could inhibit the expression of Ki-67 and mTOR in mouse melanoma." (PMID 40708947, 2025). "Interestingly, autophagy is regulated by the mTOR pathway and plays a dual role in melanoma progression." (PMID 41429766, 2025). "What distinguishes this study is its comparative evaluation of three mechanistically distinct generations of mTOR inhibitors, analyzed not only for their molecular effects but also for their impact on melanoma cell morphology, migration dynamics, and extracellular matrix remodeling." (PMID 40869090, 2025). "Understanding the interplay between melanogenesis and the PI3K/AKT/mTOR pathway may provide insights into therapeutic targets for melanoma treatment." (PMID 40708947, 2025).
melanoma (continued). "Combined with disease and drug target databases, we found that salidroside may modulate the PI3K-Akt signaling pathway by targeting mTOR, thus exerting a therapeutic effect on melanoma." (PMID 40708947, 2025). "The PI3K/Akt/mTOR pathway has been thoroughly studied in melanoma." (PMID 39844566, 2025). "However, how salidroside achieves its anti-melanoma effect in melanoma by regulating PI3K/Akt/mTOR remains poorly understood." (PMID 40708947, 2025). "RNA-seq and proteomic profiling of 3D cultures of patient-derived melanoma explants demonstrated that inhibition of the miR-99b~125a~let-7e cluster reprogrammed the tumor microenvironment, enhancing immune activation and suppressing mTOR signaling." (PMID 41550951, 2025). "Notably, inhibiting the PI3K/Akt/mTOR in melanoma cells has shown a potential to suppress their growth and migration." (PMID 39844566, 2025). "And block the melanoma cell cycle by inhibiting the PI3K/Akt/mTOR signaling pathwa." (PMID 40932870, 2025). "Correspondingly, recent research has corroborated that selective inhibition of these pathways(mTOR and ERBB) presents a promising therapeutic avenue for melanoma variants that exhibit resistance to PD-1 monoclonal antibodies, which are critical in the disease’s advancement." (PMID 40191195, 2025). "Indeed BRAF mutations frequently co-occur with inactivation of PTEN in melanomas, eliciting activation of the proproliferative MAPK pathway and PI3K/AKT/mTOR signaling, respectively." (PMID 39636745, 2025). "Moreover, the present study findings confirmed that the inhibition of PI3K/Akt signaling by directly targeting mTOR is a feasible strategy for melanoma management." (PMID 40708947, 2025). "Finally, we explored the relationship between USP22 and melanoma vulnerability to ferroptosis and found that USP22 inhibition sensitizes melanoma to RSL3‐induced ferroptosis through inhibiting PI3K/Akt/mTOR pathway‐mediated SCD expression." (PMID 39135915, 2024). "In addition to quercetin, compounds such as curcumin and fisetin have been shown to inhibit the PI3K/AKT/mTOR pathway, suggesting that they can inhibit a variety of cancers, especially melanoma." (PMID 39161800, 2024). "Dysregulation of the PI3K/AKT/mTOR pathways contributes to the pathogenesis of melanoma." (PMID 38334632, 2024). "It suppresses the phosphorylation and activation of PI3K, AKT, and mTOR in melanoma cells." (PMID 39371094, 2024). "Previously, we reported that inhibition of PI3K/Akt/mTOR pathway‐mediated SCD expression could sensitize melanoma to ferroptosis." (PMID 39135915, 2024). "Similarly, in the case of melanoma, Piezo1 promotes the malignant progression of the disease through Akt/mTOR signaling." (PMID 38690080, 2024). "Furthermore, 70% of patients with melanoma displayed mutations in genes in key signaling pathways such as PTEN, which leads to the hyperactivation of the PI3K/Akt/mTOR pathway." (PMID 38338464, 2024). "Sinomenine regulates autophagy via the PI3K/Akt/mTOR pathway and plays an anti-melanoma role." (PMID 38668684, 2024). "Moreover, adipocytes affect melanoma cell invasion by prompting the production of oncogenic proteins such as cyclin D1 and cyclooxygenase 2 and by stimulating the Akt/mTOR pathway." (PMID 38921444, 2024). "Together, these observations strongly support that targeting the PI3K/Akt/mTOR pathway could represent a successful strategy to overcome therapy resistance while specifically suppressing CSCs and tumor angiogenesis in melanoma." (PMID 39199632, 2024). "Moreover, studies have demonstrated that the PI3K/AKT/mTOR signaling pathway can affect the proliferation and metastasis of melanoma by altering the expression of HIF-1α." (PMID 38771435, 2024). "However, in melanoma cells (A375 and C8161 lines), the induction of cell cycle arrest at the G2/M phase was postulated to occur via the Akt/mTOR pathway." (PMID 38791608, 2024).